ANKRD26 (ankyrin repeat domain 26)
Description:
Acts as a regulator of adipogenesis. Involved in the regulation of the feeding behavior.
Synonyms: KIAA1074; THC2; bA145E8.1
Tractability: PROTAC: ubiquitination databases record sites on it.
Gene: Protein-coding gene on chromosome 10 (26,973,793 to 27,100,517, reverse strand). Ensembl gene ENSG00000107890.
Subcellular location (Human Protein Atlas): Golgi apparatus; Cytosol; Vesicles
Pathways (Reactome):
Signal Transduction: RND1 GTPase cycle; RND2 GTPase cycle; RND3 GTPase cycle
Gene Ontology:
Molecular function: protein binding
Biological process: negative regulation of fat cell differentiation
Cellular component: centrosome
Genetic constraint (gnomAD): Loss-of-function variants: 106 observed, 171.09 expected, observed/expected ratio (o/e) 0.62, 90% interval 0.53 to 0.73. The upper end of that interval is the gene's LOEUF score, 0.73, which puts it in group 2 of 6, group 1 being the genes least tolerant of losing a copy. Missense variants: 1,674 observed, 1,791.7 expected, observed/expected ratio (o/e) 0.93, 90% interval 0.9 to 0.97. Synonymous variants: 573 observed, 625.86 expected, observed/expected ratio (o/e) 0.92, 90% interval 0.85 to 0.98.
Gene-disease validity (ClinGen):
ClinGen rates the evidence that ANKRD26 causes each of these diseases.
thrombocytopenia 2 (autosomal dominant): Definitive.
Homologues: Orthologues: chimpanzee ANKRD26 (99% identical), macaque ANKRD26 (95% identical), rabbit ANKRD26 (69% identical), tropical clawed frog ankrd7 (32% identical), Caenorhabditis elegans lem-3 (9% identical), Drosophila melanogaster CG8679 (7% identical), zebrafish si:ch211-272n13.3 (6% identical), Caenorhabditis elegans F44E5.15 (4% identical), Drosophila melanogaster CG42391 (3% identical), Caenorhabditis elegans K07D4.2 (2% identical). Paralogues in human: ANKRD62 (29% identical), ANKRD18B (28% identical), ANKRD30B (27% identical), ANKRD18A (27% identical), ANKRD30A (26% identical), ANKRD20A1 (22% identical), ANKRD30BL (7% identical).
Diseases named in the same sentence as ANKRD26 in open-access papers:
ANKRD26 is named in the same sentence as 47 diseases in open-access papers, as found by Europe PMC text mining. Sharing a sentence is not in itself a finding about the gene and the disease. The quoted sentences say what the papers report.
Thrombocytopenia (38 papers, 2013 to 2025). A reduction in the number of circulating thrombocytes. "Among these, ANKRD26-related thrombocytopenia (ANKRD26-RT) accounts for a notable subset and is associated with variable bleeding tendencies and an increased risk of myeloid malignancies." (PMID 40863182, 2025). "To further understand the molecular basis of ANKRD26-associated thrombocytopenia, we performed mass spectrometric analysis of fluorescence-activated cell sorting (FACS)-isolated thrombocytes (mature versus young) from zebrafish of different genotypes." (PMID 40170493, 2025). "The mechanisms underlying ANKRD26 mutation-associated thrombocytopenia and hematological malignancy are still not fully understood." (PMID 40170493, 2025). "ANKRD26-related thrombocytopenia, or thrombocytopenia 2, is an inherited thrombocytopenia with mild bleeding diathesis resulting from point mutations the 5ʹUTR of the ANKRD26 gene." (PMID 35587581, 2022). "Patients with ANKRD26 variants have mostly variable bleeding symptoms, moderate-to-severe thrombocytopenia with normal-sized platelets, and reductions in α-granules and platelet GPIb." (PMID 36430862, 2022). "Clinically, ANKRD26-related thrombocytopenia is characterized by moderate bleeding and an increased risk of developing AML and MDS when compared to the general population." (PMID 35892827, 2022). "ANKRD26-related thrombocytopenia is caused by germline mutations in the 5′ regulatory region of ANKRD26 located on 10p12.1, which encodes a protein that promotes MAPK signalling and megakaryocyte development." (PMID 35892827, 2022). "Patients with ANKRD26-related thrombocytopenia have a predisposition to developing hematological malignancies, with acute myeloid leukemia and myelodysplastic syndrome most commonly described in the literature." (PMID 35587581, 2022). "Variants detected in the ANKRD26 gene are one of the most prevalent causes of inherited thrombocytopenia; however, only a small number of these patients has been identified worldwide." (PMID 36430862, 2022). "Thrombocytopenias caused by ANKRD26 are characterized by predisposition to hematological malignancies." (PMID 34237177, 2021). "Whole exome sequencing of 3 family members (I3, II8, and III5) indicated that the pathogenic mutation of thrombocytopenia was c.-128G > T within the 5′ UTR of ANKRD26 (NM_014915), which has been proven to be the cause of THC2 in a family of Finnish origin." (PMID 32351539, 2020). "Ankyrin repeat domain-containing protein 26- (ANKRD26-) related thrombocytopenia is a rare, autosomal dominant condition caused by ANKRD26 gene mutation." (PMID 31281687, 2019). "To date, the presence of familial cases of thrombocytopenia and predisposition to myeloid malignancies are the milestones for ANKRD26 mutations diagnosis." (PMID 28955657, 2017). "The RUNX1 or ANKRD26 mutations should be suspected among patients with thrombocytopenia with a family history of bleeding and/or MDS/AML." (PMID 28955657, 2017). "The ETV6 mutations, such as RUNX1 and ANKRD26 mutations, should be suspected among patients with thrombocytopenia with a family history of bleeding and/or hematologic malignances." (PMID 28955657, 2017). "It is interesting that a paralog of ANKRD11, namely ANKRD26, is linked to thrombocytopenia inherited in a dominant manner and that ANKDR11 itself is expressed in bone marrow at high level." (PMID 28422132, 2017). "Thrombocytopenia 2 (THC2) is an inherited disorder caused by monoallelic single nucleotide substitutions in the 5'UTR of the ANKRD26 gene." (PMID 28100250, 2017). "Future studies to dissect the functional relevance of NINJ1 in ANKRD26 mutation-associated thrombocytopenia could shed new light on its broader implications for other hematological and inflammatory disorders." (PMID 40170493, 2025). "Mutations in ANKRD26 have been linked to thrombocytopenia and myeloid malignancies in humans." (PMID 32366837, 2020).
Thrombocytopenia (continued). "Furthermore, this study emphasizes the clinical vulnerability of individuals with germline RUNX1-FPDMM—as well as those with other thrombocytopenia-associated predispositions such as ETV6 or ANKRD26—and underscores the need for dedicated healthcare infrastructure." (PMID 41458504, 2025). "In addition, PaCSs have been observed in neutrophils of patients with Shwachman–Diamond syndrome due to mutation of the SBDS gene involved in ribosome biogenesis and function, and in platelets and megakaryocytes of another genetic disease, ANKRD26 gene-mutated thrombocytopenia." (PMID 24358206, 2013). "Recently, a deletion of the 10p12.1 chromosome in the THC2 locus involving exons 1 to 4 of ANKRD26 was described in a family of patients affected by thrombocytopenia." (PMID 40806462, 2025). "We conclude that ANKRD26 overexpression, resulting from either hereditary or acquired mechanisms, contributes to thrombocytopenia, thrombosis and hematologic malignancies." (PMID 40170493, 2025). "Thrombocytopenia 2 (THC2) is a rare inherited thrombocytopenia, typically associated with mutations in the 5′-untranslated region (5′-UTR) of ankyrin repeat domain-containing protein 26 (ANKRD26)." (PMID 40170493, 2025). "ANKRD26 (Ankyrin Repeat Domain-Containing 26)-related thrombocytopenia (ANKRD26-RT) accounted for 10% of IT cases in a large Italian cohort, making it one of the most common inherited thrombocytopenias." (PMID 40863182, 2025). "Mutations in the genes ANKRD26, RUNX1, and ETV6 cause three clinically overlapping thrombocytopenias characterized by a predisposition to hematological neoplasms." (PMID 39791724, 2024). "For example, germline variants in RUNX1, ANKRD26, and ETV6 all predispose to thrombocytopenia and hematologic malignancies." (PMID 38203823, 2024). "We found that GP1BA-, MYH9-, ACTN1-, and ANKRD26-related thrombocytopenias are the most frequent diseases diagnosed with a highly variable clinical course and long-term prognosis." (PMID 36507135, 2022). "We review the clinical features and biological mechanisms of ANKRD26-related thrombocytopenia and summarize known cases in the literature." (PMID 35587581, 2022). "The main diagnoses were Wiskott–Aldrich syndrome, MYH9-related disorder and ANKRD26-related thrombocytopenia." (PMID 33919295, 2021). "Once a diagnosis of inherited thrombocytopenia with germline mutation in RUNX1, ANKRD26, or ETV6 is established, close and long-term surveillance is mandatory given the lifelong increased risk of developing hematologic malignancies." (PMID 33802366, 2021). "One of these gene pairings (MASTL to ANKRD26) is corroborated by the fact that the same two genes are elite disease genes for the same disease (Thrombocytopenia 2) in MalaCards." (PMID 28605766, 2017). "For instance, Patient 4, a 19-year-old male with a history of longstanding unexplained thrombocytopenia and learning disability, developed acute myeloid leukemia and was suspected to carry a pathogenic variant in RUNX1,ETV6 or ANKRD26." (PMID 28104920, 2017). "Currently, the use of TPO agonists is approved for immune thrombocytopenia; nevertheless, several recent reports suggest their possible use in some IPD, such as the Wiskott–Aldrich syndrome, MYH9-related disorder, ANKRD26-related thrombocytopenia, and the GPIIb/IIIa- related thrombocytopenia." (PMID 41225960, 2025). "Our findings could help develop a targeted therapeutic for ANKRD26-related thrombocytopenia and hematologic malignancy." (PMID 40170493, 2025). "It was suggested that the RUNX1/FLI1 complex negatively regulates ANKRD26 expression and that mutations in 5′-UTR of ANKRD26 disrupt RUNX1/FLI1 inhibition, which would lead to overexpression of ANKRD26 in megakaryocytes and defective proplatelet formation, and thus thrombocytopenia in patients." (PMID 40170493, 2025). "ANKRD26 is a gene located at 10p12.1 that regulates megakaryocyte development and thrombocytopenia." (PMID 38203823, 2024).
Thrombocytopenia (continued). "Variants of ANKRD26 and of transcription factors ETV6 and RUNX1, which are associated with autosomal dominant (AD) inherited disorders, represent almost one-quarter of inherited thrombocytopenia cases." (PMID 36430862, 2022). "Insofar management for thrombocytopenias associated with RUNX1, ANKRD26, or ETV6 mutations are concerned, a cytogenetic bone marrow examination is recommende at the time of diagnosis, particularly if the mutations have already been reported and have proven pathogenicity." (PMID 33926054, 2021). "473A > G in ANKRD26 was also reported segregating with thrombocytopenia." (PMID 32351539, 2020). "RUNX1, ANKRD26, MYH9, ACTN1, and GP1BB had ranks of 1, 3, 8, 16, and 74, respectively, with none of the other loci in the top 20 ranks being known to be implicated in thrombocytopenia." (PMID 28669401, 2017). "The discovery of mutations in ANKRD26, RUNX1, and the ETS family transcription factors has led to an increased understanding of the genetic basis of hereditary syndromes involving thrombocytopenia, red cell macrocytosis and leukemia and of the pathways regulated by these genes." (PMID 26102509, 2015). "Inherited mutations in ANKRD26, which is transcriptionally regulated by RUNX1 lead to a similar clinical phenotype, in which thrombocytopenia is often associated with AML and in some cases, with chronic myelogenous leukemia, chronic lymphocytic leukemia and myelodysplastic syndrome." (PMID 26102509, 2015). "Additionally, mutations in ANKRD26, RUNX1, and ETV6 may predispose patients to thrombocytopenia by disrupting normal megakaryocyte function, significantly affecting platelet production." (PMID 40757104, 2025). "In a more recent report describing the deletion of the 10p12.1 chromosome in the THC2 locus involving exons 1 to 4 of ANKRD26 in a family of patients affected by thrombocytopenia, no molecular insights were provided." (PMID 40806462, 2025). "Associated with germline mutations in the 5′ untranslated region of the gene Ankyrin Repeat Domain 26 (ANKRD26) on chromosome 10p12, Thrombocytopenia 2 is an autosomal dominant disorder that is characterized by moderate thrombocytopenia with or without bleeding propensity, similar to FPD/AML." (PMID 27248996, 2016). "Therefore, the evidence suggests that persistence of ANKRD26 expression in ANKRD26-RT leads to persistent ERK activation, which may in turn be responsible for, or contribute to, reduced megakaryocyte ploidy, impaired proplatelet formation, and subsequent thrombocytopenia." (PMID 35587581, 2022). "Wahlster and colleagues used long‐read sequencing to identify a paired‐duplication inversion of ANKRD26‐WAC 68 that leads to ANKRD26 not being silenced and consequently results in thrombocytopenia." (PMID 35514262, 2022). "Interestingly, a 5′ UTR ANKRD26 mutation was later found in the Italian kindred initially reported with an ACBD5 mutation at the THC2 locus, revealing the ACB5 to be a private rare variant linked to the THC2 locus, rather than being the cause of inherited thrombocytopenia." (PMID 27248996, 2016).
myeloid neoplasm (16 papers, 2017 to 2025). Proliferation of myeloid cells originating from a primitive stem cell. "ANKRD26 mutation has been previously associated with myeloid malignancies, including acute myeloid leukemia, myelodysplastic syndrome, and chronic myeloid leukemia." (PMID 31281687, 2019). "While ANKRD26-RT is associated with myeloid neoplasms, the c.−118C > G variant may confer a lower oncogenic potential." (PMID 40863182, 2025). "Of note, in 2016 the World Health Organization classification included myeloid malignancies arising from germline mutations in ANKRD26, RUNX1, and ETV6 into a new category defined as “Myeloid neoplasms with germline predisposition and pre-existing platelet disorders”." (PMID 33802366, 2021). "Given the association of variants in the ANKRD26 5'UTR with myeloid neoplasms, we investigated whether, and to what extent, mutations in this region contribute to apparently sporadic AML." (PMID 28100250, 2017). "A subset of patients with familial thrombocytopenia are at increased risk of developing myeloid neoplasms during their life time, particularly those with germline autosomal dominant mutations in the RUNX1, ANKRD26, and ETV6 genes." (PMID 33802366, 2021).
acute myeloid leukemia (10 papers, 2017 to 2025). Acute myeloid leukemia (AML) is a group of neoplasms arising from precursor cells committed to the myeloid cell-line differentiation. "For hematological malignancies, hereditary predisposition was first identified in chronic lymphocytic leukemia (CLL) and acute myeloid leukemia (AML), which has led to the identification of several germline mutations, such as RUNX1, CEBPA, GATA2, ANKRD26, DDX41 and ETV6 mutations." (PMID 36998465, 2023). "ANKRD26-related thrombocytopenia (ANKRD26-RT), ETV6-related thrombocytopenia (ETV6-RT), and familial platelet disorder predisposing to acute myeloid leukemia (FPD/AML) are three HT linked to specific predispositions to hematological malignancies." (PMID 41167018, 2025).
Obesity (8 papers, 2012 to 2023). Accumulation of substantial excess body fat. "ANKRD26 is located at chromosome 10p12, a locus previously associated with maternally inherited obesity in humans." (PMID 31801613, 2019). "A mouse model also confirmed that partial inactivation of the ANKRD26 gene caused the development of extreme obesity, insulin resistance and gigantism, which is in line with our findings of DM and BMI." (PMID 27790247, 2016). "Partial inactivation of the Ankyrin repeat domain 26 (Ankrd26) gene causes obesity and diabetes in mice and increases spontaneous and induced adipogenesis in mouse embryonic fibroblasts." (PMID 22666460, 2012). "Although the authors did not identify whether the methylation of the ANKRD26 gene was caused by obesity or an inherited trait, a study in rodents showed that the consumption of a diet rich in saturated fat induces methylation of the ANKRD26 gene." (PMID 37296485, 2023). "Indeed, persistence of the high-fat diet regimen and the onset of obesity in mice causes epigenetic silencing of the Ankrd26 mRNA expression due to the specific hyper-methylation of the Ankrd26 promoter at the CpG sites − 436 and − 431 bp." (PMID 31801613, 2019). "In support of this last statement are our previous data obtained in mutant mice, in which removal of the region encoding amino acids 1212–1710, encompassing part of the spectrin like helices and all the C-terminus of Ankrd26, cause extreme hyperphagia and severe obesity." (PMID 22666460, 2012). "Only two rare single-nucleotide polymorphisms (SNPs) at the ANKRD26 gene, the rs139049098 (minor allele frequency, MAF: C = 0.0004/2) and the rs191015656 (MAF: A = 0.0004/2), have been so far associated with severe obesity in humans." (PMID 31801613, 2019). "Ankyrin Repeat Domain 26 (Ankrd26) is involved in the development of both obesity and diabetes in mice and is modulated by environmentally induced epigenetic modifications." (PMID 31801613, 2019). "Altogether, this evidence suggests that the Ankrd26 gene plays a key role in the events contributing to obesity development and related dysfunction." (PMID 31801613, 2019). "We have further explored the potential clinical relevance of the epigenetic silencing of ANKRD26 by correlating both the ANKRD26 gene expression and DNA methylation to obesity-related endophenotypes." (PMID 31801613, 2019). "Mice with partial inactivation of the Ankrd26 gene develop marked hyperphagia, severe obesity and an unusual form of diabetes in which white adipose tissue preserves its sensitivity to insulin." (PMID 22666460, 2012). "Furthermore, we demonstrated that diet-induced obesity in mice led to a hyper-methylation of the Ankrd26 (Ankyrin repeat domain containing 26) gene promoter, which further contributed to increased secretion of pro-inflammatory factors in AT." (PMID 35883538, 2022). "This study aims at investigating whether impaired ANKRD26 gene expression and methylation occur in human obesity and whether they correlate to the phenotype of these subjects." (PMID 31801613, 2019). "In addition to ours, other groups have further described Ankrd26 as a gene involved in the regulation of feeding behavior and in the development of both obesity and diabetes in mice." (PMID 31801613, 2019). "This supports the hypothesis that similar changes of DNA methylation, occurring in the human ANKRD26 gene, might be the result of increased BMI/adiposity typical of obesity." (PMID 31801613, 2019). "Therefore, whether the observed epigenetic downregulation of the ANKRD26 gene precedes or is a consequence of obesity and thus, whether the increased CpG methylation at the ANKRD26 promoter has a role in the regulation of BMI and/or is predictive of obesity onset deserves to be further investigated." (PMID 31801613, 2019).
Obesity (continued). "We also found that the ANKRD26 gene expression in the blood cells correlates positively to its mRNA expression in abdominal VAT, a tissue relevant to ANKRD26 protein function, suggesting that perturbation of ANKRD26 expression is biologically relevant to obesity." (PMID 31801613, 2019). "Next, the Ankrd26 gene expression was assessed in vitro by exposing 3T3-L1 adipocytes to either palmitate or oleate, representing saturated and unsaturated fatty acid species, which are abundant in the HFD, or alternatively to leptin, whose levels raise through obesity development." (PMID 28266632, 2017).